NSMCE3 (NSE3 component of SMC5/6 complex)
Description:
Component of the SMC5-SMC6 complex, a complex involved in repair of DNA double-strand breaks by homologous recombination. The complex may promote sister chromatid homologous recombination by recruiting the SMC1-SMC3 cohesin complex to double-strand breaks. The complex is required for telomere maintenance via recombination in ALT (alternative lengthening of telomeres) cell lines and mediates sumoylation of shelterin complex (telosome) components which is proposed to lead to shelterin complex disassembly in ALT-associated PML bodies (APBs). In vitro enhances ubiquitin ligase activity of NSMCE1. Proposed to act through recruitment and/or stabilization of the Ubl-conjugating enzyme (E2) at the E3:substrate complex. May be a growth suppressor that facilitates the entry of the cell into cell cycle arrest (By similarity).
Synonyms: HCA4; MAGEG1; NDNL2; MAGEL3; NSE3; LICS
Tractability: PROTAC: ubiquitination databases record sites on it; its protein half-life has been measured.
Gene: Protein-coding gene on chromosome 15 (29,264,989 to 29,269,822, reverse strand). Ensembl gene ENSG00000185115.
Subcellular location: Cytoplasm; Nucleus; Chromosome, telomere
Pathways (Reactome):
Metabolism of proteins: SUMOylation of DNA damage response and repair proteins
Gene Ontology:
Molecular function: protein binding; protein dimerization activity
Biological process: cellular response to hydroxyurea; cellular response to radiation; cellular response to UV; DNA repair; positive regulation of protein ubiquitination; chromatin looping; double-strand break repair via homologous recombination; negative regulation of transcription by RNA polymerase II; protein sumoylation; regulation of telomere maintenance
Cellular component: nucleus; Smc5-Smc6 complex; chromosome, telomeric region; nucleoplasm; cytoplasm
Genetic constraint (gnomAD): Missense variants: 452 observed, 393.94 expected, observed/expected ratio (o/e) 1.15, 90% interval 1.06 to 1.24. Synonymous variants: 214 observed, 174.98 expected, observed/expected ratio (o/e) 1.22, 90% interval 1.09 to 1.37.
Gene-disease validity (ClinGen):
ClinGen rates the evidence that NSMCE3 causes each of these diseases.
lung disease, immunodeficiency, and chromosome breakage syndrome; (autosomal recessive): Limited.
Homologues: Orthologues: rat Mageb10 (68% identical), mouse Nscme3l (64% identical), rabbit NSMCE3 (55% identical), tropical clawed frog nsmce3 (43% identical). Paralogues in human: MAGEF1 (43% identical), MAGEL2 (40% identical), MAGED2 (37% identical), MAGEE1 (36% identical), MAGEB16 (35% identical), TRO (35% identical), MAGED1 (34% identical), MAGED4 (34% identical), MAGED4B (34% identical), MAGEB10 (33% identical), NDN (33% identical), MAGEA10 (33% identical), and 25 more.
Diseases named in the same sentence as NSMCE3 in open-access papers:
NSMCE3 is named in the same sentence as 25 diseases in open-access papers, as found by Europe PMC text mining. Sharing a sentence is not in itself a finding about the gene and the disease. The quoted sentences say what the papers report.
lung disease (7 papers, 2016 to 2025). "Our genetic studies of 2 unrelated kindreds with remarkably similar clinical histories provide a strong link between missense mutations in NSMCE3 and the phenotypes of chromosomal instability and failure to thrive with infectious (viral) pneumonia ending in fatal lung disease." (PMID 27427983, 2016). "NSMCE3 deficiency, also known as lung disease, immunodeficiency, and chromosome breakage syndrome (LICS), is an AR disorder characterized by failure to thrive, immune deficiency, and progressive pediatric lung disease due to viral infection that may be fatal." (PMID 36986362, 2023). "The remaining 11 genes in the region encode proteins associated with neurologic disorders (APBA2, CHRFAM7A, MTMR10, FAN1), skin and eye pigmentation or development (OCA2, HERC2, TJP1, TRPM1), nephritis (ARHGAP11B, MTMR10, FAN1), and lung disease (ENTREP2, NSMCE3)." (PMID 40013929, 2025).
Insulin resistance (2 papers, 2023 to 2024). Increased resistance towards insulin, that is, diminished effectiveness of insulin in reducing blood glucose levels. "For example, SMC5/6-destabilizing mutations in NSMCE3 cause lung disease-immunodeficiency-chromosomal breakage syndrome (LICS), and NSMCE2 or SMC5 mutations result in primordial dwarfism and insulin resistance." (PMID 38886582, 2024).
acute respiratory distress syndrome (1 paper, 2016). Progressive and life-threatening pulmonary distress in the absence of an underlying pulmonary condition, usually following major trauma or surgery. "This work associates missense mutations in NSMCE3 with an autosomal recessive chromosome breakage syndrome that leads to defective T and B cell function and acute respiratory distress syndrome in early childhood." (PMID 27427983, 2016).
pneumonia (1 paper, 2016). An acute, acute and chronic, or chronic inflammation focally or diffusely affecting the lung parenchyma, caused by an infection in one or both of the lungs (by bacteria, viruses, fungi, or mycoplasma.). "We recommend development of a clinical assay for the replication recovery defect and for NSMCE3 mutations and consideration of this disorder for children with unexplained, rapid pulmonary failure following multiple virus-induced pneumonias." (PMID 27427983, 2016).
infection (1 paper, 2025). The state of being infected such as from the introduction of a foreign agent such as serum, vaccine, antigenic substance or organism. "NSMCE3 is known to undergo proteasomal degradation following HBV infection, and its downregulation shows that our infection model can capture replication-dependent host responses." (PMID 41201845, 2025).
NSMCE3 also shares sentences with these, for which no sentence is quoted: immune deficiency (2 papers); melanoma (2); atypical ductal hyperplasia (1); autism (1); Bartter syndrome (1); Failure to thrive (1); genetic disorders (1); glioblastoma multiforme (1); glioma (1); immunodeficiency (1); Intellectual disability (1); invasive carcinoma (1); lung disease-immunodeficiency-chromosomal breakage syndrome (1); male infertility (1); microcephalic primordial dwarfism (1); nephritis (1); neurologic disorders (1); pancreatic cancer (1); primordial dwarfism (1); tumor (1).